NOTCH1 (notch receptor 1)
Diseases named in the same sentence as NOTCH1 in open-access papers (continued):
Sharing a sentence is not in itself a finding about the gene and the disease.
liver cancer (43 papers, 2013 to 2026). An epithelial or non-epithelial malignant neoplasm that arises from the liver. "In biopsies of hepatic cancer, high expression levels of Notch1 and Hes1 were associated with VM." (PMID 31993365, 2019). "Activation of the Notch1 signaling pathway enhances the stemness of liver cancer stem cells and drives liver cancer progression." (PMID 41425729, 2025). "Antibodies targeting Jag1 and Notch1 have shown remarkable potential in treating N‐Ras‐induced primary liver cancer in mice." (PMID 39113232, 2024). "In a later study conducted on primary liver cancer mouse models, it was reported that Notch1 inhibition reduced HCC-like tumors but strongly increased CCA-like nodules, underlining a possible highly context-dependent activity of Notch1." (PMID 39766289, 2024). "Further exploration found that KK-LC-1, through interaction with presenilin-1, activates the Notch1 signaling pathway and then it plays a role in promoting the growth, migration and invasion of liver cancer, thus triggering the tumorigenesis of liver cancer." (PMID 35855340, 2022). "Meanwhile, FXR also positively regulated Numb expression, contributing to a feedback circuit, which decreased Notch1 activity and directed Sox9+ cells asymmetric division to prevent the development of liver cancer." (PMID 33845903, 2021). "In this sense, it has been reported that overexpression of Notch1-IC in lung and liver cancer cells increases resistance to cisplatin." (PMID 31605148, 2020). "In a larger data set from 423 of liver cancer patients (The Cancer Genome Atlas-Cancer Genome, TCGA liver cancer), both NOTCH1 and SNAIL1 showed a significant expression correlation, suggesting a potential for the two proteins functioning together." (PMID 30405889, 2018). "Anti-Notch2 treatment blocks the development of a broad range of tumors in a mouse model with primary liver cancer whereas the inhibition of Notch1 increases the development of cholangiocarcinoma like tumors." (PMID 27167202, 2016). "In contrast, two research groups revealed that the activated intracellular domain of Notch1 or Notch2 induces liver cancer development." (PMID 26416455, 2015). "Notch-1 has been shown to play an important tumor-suppressive role in epidermal keratinocytes and studies in cervical, prostate, lung, brain and liver cancers have also suggested tumor-suppressive function for Notch signaling." (PMID 24223915, 2013). "Additionally, FXR regulates asymmetric cell division of Sox9+ cells via the Notch1 pathway to prevent liver cancer development." (PMID 39940889, 2025). "The activation of Notch1 was found to be one of the key events in the development of liver cancer." (PMID 33845903, 2021). "For example, Kong demonstrated the upregulation of Interleukin-7 receptor (IL-7R) could facilitate the proliferative and migratory activities of liver cancer cells through NF-κB and Notch1 pathways." (PMID 34544391, 2021). "To confirm the activation of Notch1 signalling by KK‐LC‐1 in liver cancer, we treated Huh7 cells with 5 μmol/L of N‐[N‐(3,5‐difluorophenacetyl)‐L‐alanyl]‐S‐phenylglycine t‐butylester (DAPT; Selleck, Houston, TX, USA) for three days to suppress the release of NICD1." (PMID 30895661, 2019). "Therefore, HULC increases the cellular autophagy by increasing LC3II dependent on Sirt1.Noteworthy, excessive HULC reduces the expression of PTEN, β-catenin and enhances the expression of SAPK/JUNK, PKM2, CDK2, NOTCH1, C-Jun in liver cancer cells." (PMID 29895332, 2018).
liver cancer (continued). "Taken together, Notch1 positively correlated with the activation of Wnt/β-catenin, suggesting that Notch1 may be downstream of Wnt/β-catenin signaling in sphere-forming liver cancer stem cells." (PMID 26735577, 2016). "Since among the secreted proteins were identified proteins involved in cell adhesion, we analysed whether Notch1 could play a role in the invasion of liver cancer cells." (PMID 27167202, 2016). "Here, we found that Strawberry Notch 1 (SBNO1) is upregulated in several cancer entities and elucidated the role of SBNO1 in liver cancer development." (PMID 41649174, 2026). "XH regulated the MCP-1 protein and reduced the expression of Notch1 and HES-1 protein in liver cancer." (PMID 33923053, 2021). "Our findings suggest that FXR represses Notch1 expression and directs ACD of Sox9+ cells to prevent the development of liver cancer." (PMID 33845903, 2021). "In liver cancer, b-AP15 kills human liver cells by enhancing ER stress and blocking the Wnt/Notch1 pathway." (PMID 32391376, 2020). "For this, the TCGA liver cancer data were analyzed for expression of TBC1D15 and NOTCH1 in relation to HCC stage." (PMID 32555153, 2020). "Meanwhile, the direct target gene of NOTCH1, ABCG2 were also decreased in liver cancer cells which was down-regulated NAP1L1 expression." (PMID 31516385, 2019). "In hepatic cancer HepG2 and MHCC97-H cell lines, the Notch1 expression was higher in HepG2 favoring invasiveness by inducing the EMT through an increase in vimentin and loss of E-cadherin expression." (PMID 31993365, 2019). "In order to explore biological role of Notch1 in the progression of liver cancer, we carried out a CCK8 assay when HepG2 and Hep3B cells were transfected with Notch1 siRNA or control siRNA." (PMID 28507277, 2017). "A set 105 interaction partners of USP15 contained two liver cancer genes, LRRK and NOTCH1." (PMID 36900163, 2023). "Our results demonstrated that MSI2 maintained the stemness of CD44v6+ LCSCs by activating Notch1 signaling through the interaction with LFNG, which could be a potential molecular target for stem cell-targeted therapy for liver cancer." (PMID 31888685, 2019). "In summary, our study clarified a key role of Notch1 and RNF187 in liver cancer metastasis." (PMID 31477177, 2019). "Moreover, NOTCH1 and ABCG2 protein expression levels were decreased concurrent with NAP1L1 down-regulation in liver cancer cells by WB analysis." (PMID 31516385, 2019). "Therefore, we aimed to determine whether FXR could repress Notch1 expression and direct liver CSC asymmetrical division to prevent the development of liver cancer." (PMID 33845903, 2021).
esophageal cancer (37 papers, 2012 to 2025). A primary or metastatic malignant neoplasm involving the esophagus. "NOTCH1 mutations are highly selected for and take over the majority of the human esophagus by middle age but, by contrast, are comparatively rare in esophageal cancers, suggesting they drive clonal selection but hamper carcinogenesis." (PMID 38870403, 2024). "Studies have shown that the Notch1 mutation suppresses the metastasis of esophageal cancer cells, thereby potentially impeding the malignant transformation of esophageal cancer." (PMID 38203782, 2024). "NOTCH1 mutant clones occupy the majority of normal human esophagus by middle age but are comparatively rare in esophageal cancers, suggesting NOTCH1 mutations drive clonal expansion but impede carcinogenesis." (PMID 36658434, 2023). "Of course, there are other potential explanations for the underrepresentation of Notch1 mutations in esophageal cancers." (PMID 30848555, 2019). "Conversely, activating Notch1 increases the susceptibility to esophageal cancer occurrence." (PMID 38203782, 2024). "NOTCH1 mutations in normal esophagus were several times higher than in esophageal cancers." (PMID 35539898, 2022). "However, the under-representation of NOTCH1 mutants in esophageal cancer compared with normal aging epithelium suggests NOTCH1 mutations may inhibit malignant transformation." (PMID 36658434, 2023). "However, certain observations, such as the higher frequency of NOTCH1 mutations in normal esophageal cells than in esophageal cancers, challenge commonly held assumptions and may call for some revision of our current lists of cancer-driving genes." (PMID 31138277, 2019). "So we further analyzed the Notch family (NOTCH1-4) variation data from esophageal carcinoma TCGA Pan-Cancer (AC, n = 87; SCC, n = 95)." (PMID 38956687, 2024). "One possible explanation for this discordance is the occurrence of an immunogenic bottleneck in the early stage of oesophageal cancer development, allowing only cells with advantageous wild type NOTCH1 to survive and expand." (PMID 37573406, 2023). "Esophageal Cancer: curcumin modulated Notch-1 signaling and suppressed NF-jB and its downstream targets involving Bcl2, cyclin D1, VEGF, and MMP-9 in oral squamous cell carcinomas." (PMID 36712505, 2022). "Notch-1 was shown to promote the invasion and metastasis of esophageal carcinoma cells by inducing epithelial-mesenchymal transition (EMT)." (PMID 25990317, 2015). "A recent study has shown that Notch1 mediates esophageal carcinoma cell invasion and metastasis by inducing EMT through upregulation of Snail." (PMID 25645291, 2015).
esophageal cancer (continued). "Subramaniam and coworkers found that curcumin inhibits Notch1 and its ligand Jagged1 in esophageal cancer cells." (PMID 24024180, 2013). "Recent research formally tested the role of NOTCH1 in mouse models of esophageal cancer." (PMID 38870403, 2024). "Intriguingly, the authors also demonstrated that mutant NOTCH1 is detrimental to cancer growth, which could explain their relative lack in oesophageal cancer." (PMID 37573406, 2023). "NOTCH1 pathways are dysregulated in skin and esophageal cancer which are dominated by SBS7a, SBS7b and SBS17a17,18, and thus these signatures may tend to promote this dysregulation." (PMID 33558557, 2021). "In a cohort of esophageal carcinomas from China, Song and colleagues found that patients with mutations in NOTCH1 had shorter survival and failed to respond to chemotherapy." (PMID 32561788, 2020). "Strikingly, while Notch1 mutant clones represent about half of the epithelial cells in individuals past 50, they are present in only ~10% of esophageal cancers." (PMID 30848555, 2019). "Curcumin inhibits Notch-1 and its ligand Jagged-1 in esophageal cancer cells." (PMID 22363450, 2012). "In accordance with that, we showed the mutation frequencies of NOTCH1 and NOTCH2 genes in esophageal mucosa of our patients (median age: 66 years, range: 49-75 years), most of whom have smoking and drinking history, were significantly higher than those in esophageal carcinoma." (PMID 35515115, 2022). "However, Notch-1 is not the only pathway active in esophageal cancer as many other cellular pathways are activated." (PMID 22363450, 2012).
small cell lung carcinoma (36 papers, 2005 to 2025). Small cell lung cancer (SCLC) is a highly aggressive malignant neoplasm, accounting for 10-15% of lung cancer cases, characterized byrapid growth, and early metastasis. "In contrast, another study showed loss-of-function mutations in all Notch receptors, although mutations in Notch1 were most frequent (25% of human small-cell lung cancer (SCLC))." (PMID 34572582, 2021). "Loss-of-function mutations in NOTCH family genes, particularly in NOTCH1, have been identified in human and mouse small cell lung cancer (SCLC) and in neuroendocrine pancreatic cells." (PMID 31443481, 2019). "In this work, the authors uncover NOTCH1 as a critical driver of immune response and survival with immunotherapy in small cell lung cancer." (PMID 40627448, 2025). "Previous studies have reported that the FACT inhibitor CBL0137 mediates small-cell lung cancer (SCLC) cell death by targeting NOTCH1." (PMID 36691066, 2023). "The inhibition of LSD1 with iadademstat (ORY-1001) reactivates NOTCH1 signaling in a chemo resistant PDX model of small cell lung cancer (SCLC)." (PMID 36011043, 2022). "Notch1 is a potential independent prognostic factor for small cell lung carcinoma patients (n = 46), with a small cohort having a high expression of Notch-1 (n = 10)." (PMID 36672573, 2022). "Accordingly, the reactivation of Notch1 suppressed the growth of neuroendocrine lung tumors and small-cell lung cancer (SCLC) by ASCL1 downregulation in vivo and in vitro." (PMID 34680255, 2021). "For example, SAHA was shown to suppressed cell growth of small-cell lung cancer (SCLC) by causing cell cycle arrest, and, in combination with cisplatin, significantly reduce the expression of Notch1." (PMID 33024443, 2020). "In contrast, NOTCH1 signaling is inhibited in neuroendocrine tumor cells, including small cell lung cancer." (PMID 32038705, 2019). "Similar findings were recently observed in a study of small cell lung cancer, in which high NOTCH1 expression was an independent favorable prognostic factor." (PMID 29721172, 2018). "In small cell lung cancer cells, overexpression of active Notch1 or 2 led to an increase in Erk activation." (PMID 18950493, 2008). "For example, in small cell lung cancer it has been shown that Notch-1 induces degradation of the Hash-1 protein." (PMID 15685243, 2005). "In fact, histone deacetylation results in Notch1 silencing in small-cell lung cancer (SCLC)." (PMID 41514582, 2025). "In addition, KDM5A can also promote the occurrence of small-cell lung cancer by inhibiting the target genes NOTCH1 and NOTCH2." (PMID 35493099, 2022). "However, in small cell lung cancer (SCLC), overexpression of Notch1 can cause G1 cell cycle block and can inhibit epithelial-to-mesenchymal transition (EMT), cell motility and cell metastatic potential." (PMID 28415716, 2017). "The role of neurogenic locus notch homolog protein 1 (NOTCH1)- and nuclear factor erythroid 2-related factor 2 (NRF2)-related pathways is highly heterogeneous in small cell lung cancer (SCLC) and, when they are both abnormally activated, they can synergistically cause neoplastic proliferation." (PMID 38791966, 2024). "Similarly, in small-cell lung cancer cells, VPA activated Notch signaling by an increase of Notch1, Notch target gene HES1, and p21 expression, which resulted in the inhibition of growth of cancer cells and cell cycle at G1 phase." (PMID 34068438, 2021). "Conversely, Notch1 signaling is very minimal or absent in NE tumors such as small-cell lung cancer (SCLC), carcinoid cancer, and MTC." (PMID 20069043, 2009). "Moreover, the mutated Kras driven lung tumors with deleted Notch1 showed increased TAZ expression and focal nuclear translocation which was frequently observed in human pulmonary adenocarcinomas and squamous cell carcinomas of the lung, but not in small cell lung carcinomas." (PMID 34257546, 2021).